OR11H2 (olfactory receptor family 11 subfamily H member 2)
Description:
Odorant receptor.
Synonyms: C14orf15; OR11H2P; OR11H13; OR11H8P
Gene: Protein-coding gene on chromosome 14 (19,712,936 to 19,713,883, reverse strand). Ensembl gene ENSG00000258453.
Subcellular location: Cell membrane
Pathways (Reactome):
Sensory Perception: Expression and translocation of olfactory receptors
Genetic constraint (gnomAD): Loss-of-function variants: 0 observed, 4.92 expected, observed/expected ratio (o/e) 0, 90% interval 0 to 0.61. That is too few expected variants to judge how well the gene tolerates losing a copy. Missense variants: 71 observed, 112.91 expected, observed/expected ratio (o/e) 0.63, 90% interval 0.52 to 0.77. Synonymous variants: 30 observed, 40.4 expected, observed/expected ratio (o/e) 0.74, 90% interval 0.56 to 1.01.
Homologues: Orthologues: dog OR11H12 (81% identical). Paralogues in human: OR11H1 (98% identical), OR11H12 (98% identical), OR11H6 (63% identical), OR11H4 (62% identical), OR11G2 (59% identical), OR11H7 (57% identical), OR11A1 (43% identical), OR9G1 (41% identical), OR10X1 (37% identical), OR9A1P (34% identical), OR9A2 (34% identical), OR9A4 (34% identical), and 21 more.